ARTN (artemin)
Diseases named in the same sentence as ARTN in open-access papers (continued):
Sharing a sentence is not in itself a finding about the gene and the disease.
depression (7 papers, 2011 to 2025). "This significant correlation may be an essential finding for translational medicine regarding artemin’s role in disrupted self-grooming behaviors associated with depression." (PMID 40867635, 2025). "Pallanti and colleagues found ARTN levels to be high in the group of patients with generalized anxiety disorder and significantly lower in patients with depression." (PMID 40867635, 2025). "An increase in anxiety–depression-like behaviors has accompanied decreased levels of artemin in the brain." (PMID 40867635, 2025). "(2025) found that circulating inflammatory proteins such as Artemin and LT‐α mediated between 5.6 and 7.8% of the effect from psoriasis to psychiatric traits, including broad depression and bipolar disorder." (PMID 40891141, 2025). "This study aims to investigate changes in artemin correlated with anxiety and depression-like behaviors in a neuroinflammation rodent model." (PMID 40867635, 2025). "In the LPS-induced depression model, artemin levels in the prefrontal cortex were found to be high after 24 h in male mice, while BDNF levels did not change." (PMID 40867635, 2025). "ARTN plasma levels are reduced in patients with major depressive disorder, and intracerebroventricular administration of ARTN shows dose-dependent antidepressant effects in mice, potentially via modulation of neuronal plasticity." (PMID 30853893, 2019). "Patients with major depression had low levels of ARTN in serum." (PMID 40867635, 2025). "ARTN plays a role in pathogenesis and could be a target to improve the treatment of psychiatric disorders such as depression." (PMID 30853893, 2019). "Also the neurotrophin-3 (NT-3), GDNF and artemin (member of the GDNF family) were found to have decreased mRNA expression in the blood of patients with major depression." (PMID 22654714, 2011). "In another experimental study, artemin levels increased in the spinal cord, PFC, and hippocampus, and depression-like behaviors decreased in parallel." (PMID 40867635, 2025). "The decreased concentrations of BDNF, glial cell line-derived neurotrophic factor (GDNF), Artemin (ARTN), nerve growth factor (NGF), and vascular endothelial growth factor (VEGF) are a good repetitive finding in depression." (PMID 35369081, 2022). "In patients diagnosed with generalized anxiety disorder who did not receive drug treatment and did not have depression, artemin mRNA levels in serum were found to be higher than those of healthy controls." (PMID 40867635, 2025).
endometrial carcinoma (5 papers, 2011 to 2022). A malignant tumor arising from the epithelium that lines the cavity of the uterine body. "Higher ARTN expression in endometrial carcinoma (EC) was associated with enhanced invasiveness, a higher tumor grade, and lymphatic metastasis." (PMID 36471885, 2022). "For example, in endometrial cancer, ARTN specifically regulates CD24 to stimulate endometrial cancer cell resistance to doxorubicin and paclitaxel." (PMID 34496868, 2021). "It has been previously reported that ARTN activates AKT to mediate its oncogenic effects in endometrial carcinoma cells." (PMID 22060274, 2011). "Furthermore, the depletion of ARTN expression inhibits survival, invasion and anchorage-independent growth of both breast and endometrial cancer cells, while the forced expression of ARTN promotes these cellular behaviors." (PMID 25120606, 2014). "Similarly, artemin augments the expression of AKT1 and thereby accentuates the invasive potential of endometrial carcinomas." (PMID 22891163, 2012).
esophageal cancer (4 papers, 2011 to 2022). A primary or metastatic malignant neoplasm involving the esophagus. "ARTN function is suppressed by miR-223 overexpression, which reduces esophageal cancer cell migration and invasion." (PMID 35205115, 2022). "To further study the potential relationship between miR-223 and ARTN, we analyzed miR-223 and ARTN expression level in esophageal cancer tissues." (PMID 21453483, 2011). "In most cases, ARTN levels in normal esophageal tissue were significantly lower than those in esophageal cancer tissue." (PMID 21453483, 2011). "The expression level of ARTN in four human esophageal carcinoma cell lines was also examined by Western blot." (PMID 21453483, 2011). "In conclusion, ARTN expression levels were significantly higher in esophageal carcinoma than in adjacent noninvasive tissues, and ARTN promoted migration and invasion of esophageal carcinoma cells." (PMID 21453483, 2011). "ARTN expression levels were higher in esophageal carcinoma tissue than in the adjacent tissue and was differentially expressed in various esophageal carcinoma cell lines." (PMID 21453483, 2011). "In this study, we discovered that the expression of ARTN in esophageal carcinoma tissue was higher than that of adjacent tissues, and down-regulation of artemin expression mitigated KYSE150 cell migration and invasiveness." (PMID 21453483, 2011). "Regulation of miR-223 expression affected the expression of ARTN as well as cell migration and invasion in esophageal carcinoma cells." (PMID 21453483, 2011). "In the present study, we demonstrate that ARTN expression is significantly higher in esophageal carcinoma than in adjacent noninvasive tissues, and that ARTN promotes migration and invasion of esophageal carcinoma cells." (PMID 21453483, 2011). "ARTN expression levels were detected in esophageal carcinoma cell lines KYSE-150, KYSE-510, EC-9706, TE13, esophageal cancer tissues and paired non-cancerous tissues by Western blot." (PMID 21453483, 2011). "To develop potential therapy targeting ARTN, we studied the roles of miR-223 in the migration and invasion of human esophageal carcinoma." (PMID 21453483, 2011). "They found that esophageal cancer cells display low miR-223 and high artemin levels." (PMID 35205115, 2022). "Interestingly transfection with a mir-223 vector decreases expression of artemin and thereby suppresses tumor growth in esophageal carcinomas." (PMID 22891163, 2012). "Increased expression of artemin is also seen in esophageal carcinomas." (PMID 22891163, 2012). "Finally, we validated that ARTN is a direct target of miR-223 in the context of human esophageal carcinoma." (PMID 21453483, 2011). "Interestingly, ARTN expression levels were higher in KYSE150 and KYSE510 than in EC9706 and TE13 cell lines, suggesting that expression of miR-223 was inversely related to ARTN protein level in esophageal carcinoma." (PMID 21453483, 2011).
lung carcinoma (4 papers, 2022 to 2023). "Transwell assay showed that interference with ARTN expression inhibited the invasion and migration ability of lung cancer cells." (PMID 37674202, 2023). "In this study, we used siRNA to interfere with ARTN expression in lung cancer cells to investigate the effect of ARTN on non-small cell lung cancer." (PMID 37674202, 2023). "Kaplan–Meier plotter analysis showed that lung cancer patients with high ARTN expression had poor survival." (PMID 37674202, 2023). "Cell function experiments demonstrate the ability of the signature gene ARTN to promote cancer and maintain the stemness of lung cancer cells." (PMID 37674202, 2023). "MicroRNA-223 was reported as a vital tumor regulator in many cancers, and it could promote lung cancer cell invasion and influence the ability of migration and invasion via moderating the expression level of artemin (ARTN)." (PMID 35075362, 2022). "Studies have shown that Artemin enhances the resistance of lung cancer cells to radiotherapy through the TWIST1-BCL2 pathway, suggesting that Ter cells may inhibit the therapeutic effects of radiotherapy through Artemin." (PMID 35799264, 2022). "However, ARTN has little to no reported effect on maintaining lung cancer cell stemness." (PMID 37674202, 2023).
migraine (4 papers, 2016 to 2024). "Thus, the role of the TRPV1 in migraine pain is still controversial to date, and the downstream regulatory mechanisms underlying the actions of artemin and GFRα3 on migraine pain require to be studied further." (PMID 27600145, 2016). "Artemin is thought to be an important endogenous mediator for inflammation, migraine, burning mouth syndrome, and neuropathic cold allodynia." (PMID 32116521, 2020). "In consideration of NTG-induced delayed onset inflammation in migraine model rats, the mRNA expression of artemin in the dura mater was detected after NTG or NS administration for 2, 4 and 6 h each." (PMID 27600145, 2016). "In this study, we explored the locations and expression of artemin and its selective receptor GFRα3 in an animal model of migraine, with special attention given to their possible involvement in the pathogenesis of migraine." (PMID 27600145, 2016). "By binding to GFRα3, one of the GDNF family receptors, ARTN could exert an impact on intracellular signaling pathways that are crucial in the pathophysiology of bone pain and migraine." (PMID 39508645, 2024). "Several researchers have found increased levels of artemin associated with tissue damage or inflammation in rodent pain models, such as CFA injection and the nitroglycerin (NTG) migraine model." (PMID 32116521, 2020). "Meanwhile, the number of GFRα3 immunoreactive TG neurons was increased after NTG treatment, indicating that the release of artemin from the vascular smooth muscle cells may activate the peripheral trigeminal nerve via binding GFRα3 in a rat migraine model." (PMID 27600145, 2016). "Taken together, artemin and its selective receptor GFRα3 might be novel targets for therapeutic strategies of migraine." (PMID 27600145, 2016). "The distribution of artemin and GFRα3 in the dura mater raises an anatomy supports that they may be involved in migraine." (PMID 27600145, 2016). "In summary, our study revealed that the enhanced activities of artemin and GFRα3 might be critical processes in migraine pathogenesis and serve as the possible key factor in inducing migraine pain." (PMID 27600145, 2016). "In this regard, the present study was designed to evaluate the expression of artemin in the dura mater and GFRα3 in the TG following NTG administration, so as to explore the possible mechanisms of artemin and GFRα3 underlying the pathogenesis of migraine." (PMID 27600145, 2016). "The findings suggest that artemin and GFRα3 play an important role in the pathogenesis of migraine and may represent potential therapeutic targets for the treatment of migraine." (PMID 27600145, 2016). "In this study we evaluated the expression of artemin and GFRα3 in an animal migraine model that may be relevant for migraine." (PMID 27600145, 2016). "In addition, the detection of the distribution of artemin and its receptor GFRα3 in the dura mater of rats suggests that artemin may contribute to migraine pain by the sensitization of dural afferents." (PMID 27600145, 2016).
non-small cell lung carcinoma (4 papers, 2014 to 2023). A group of at least three distinct histological types of lung cancer, including non-small cell squamous cell carcinoma, adenocarcinoma, and large cell carcinoma. "Molecularly, ARTN stimulates survival and anchorage-independent growth of human non-small cell lung cancer cells by upregulating BCL-2 expression." (PMID 25120606, 2014). "ARTN, RET, and GFRα3 have been demonstrated to be upregulated in non-small cell lung carcinoma (NSCLC) cells compared with their normal counterparts, while high ARTN expression also enhances the migration and invasion of NSCLC cells." (PMID 35582425, 2022).
atopic dermatitis (3 papers, 2015 to 2024). "Another important factor, in addition to Artemin, involved in the pathogenesis of atopic dermatitis is thymic stromal lymphopoietin (TSLP), which is known to activate dendritic cells and promote Th2-type immune responses." (PMID 38181031, 2024). "The accumulation of ARTN in human dermal fibroblasts from atopic dermatitis lesions induces epidermal hyper-innervation." (PMID 32252363, 2020). "A paper examining human atopic dermatitis patients’ skin showed that fibroblasts, which accumulated in the lesion, expressed increased artemin." (PMID 25889103, 2015). "Additionally, in the context of atopic dermatitis, where intense chronic itch is also observed, ARTN is released in the epidermis of patients via the activation of the aryl hydrocarbon receptor (AhR) by particulate matter in air pollution." (PMID 32252363, 2020). "Targeting ARTN signaling could be a new way to treat atopic dermatitis patients with aggravated symptoms, due to environmental pollutants, for whom steroids are ineffective." (PMID 32252363, 2020).
lymph node metastasis (3 papers, 2013 to 2022). "ARTN expression was strongly related to lymph node metastases (LNM) (P = 0.012) and recurrence (P = 0.015) in cervical cancer." (PMID 36471885, 2022). "The expression of ARTN was positively correlated with lymph node metastasis (p = 0.001) and advanced disease stages (p = 0.018)." (PMID 34422665, 2021). "We have however described a clear metastasis promoting role for ARTN in ER negative MC consistent with the association of GFRα1 and GFRα3 expression with lymph node metastasis observed in this study." (PMID 23351331, 2013).
acute myeloid leukaemia (2 papers, 2020 to 2026). "Additionally, ARTN is implicated as a pathogenic factor for certain acute myeloid leukaemia (AML) patients, which warrants further investigation." (PMID 32573073, 2020).
asthma (2 papers, 2025 to 2026). "Overall, our findings suggest that targeting artemin-driven pathways could provide a therapeutic strategy for controlling neutrophilic airway inflammation in asthma, a clinical condition typically refractory to treatment." (PMID 39229121, 2025).
chronic pancreatitis (2 papers, 2020 to 2023). A chronic inflammatory process causing damage and fibrosis of the pancreatic parenchyma. "Overexpression of ARTN in chronic pancreatitis disturbs tissue homoeostasis, leading to pancreatic fibrosis." (PMID 32573073, 2020). "Using quantitative PCR (polymerase chain reaction) and Western blot analyses, it was found that ARTN and GFRα3 were significantly overexpressed in chronic pancreatitis, and positively correlated with the severity of fibrosis." (PMID 32573073, 2020).
colon cancer (2 papers, 2018 to 2021). "A functional role of ARTN in promoting colon cancer cell oncogenicity and metastasis with CSC-like behavior and chemoresistance via p44/42 MAPK dependent expression of CDH2 was further demonstrated." (PMID 34422665, 2021). "Interestingly, ARTN, NRTN, GFRα1, and GFRα3 are found in colon tumors, potentially arising from gut nerves or associated with chronic inflammation of the intestine, which increases cancer risk, suggesting a subset of RET-expressing colon tumors may be responsive to GFL stimulation." (PMID 30666215, 2018).
colorectal cancer (2 papers, 2017 to 2021). A primary or metastatic malignant neoplasm that affects the colon or rectum. "In this study, the enhanced expression of ARTN in colorectal carcinoma (CRC) was observed; the expression of ARTN positively correlated with lymph node metastases and advanced tumor stages and predicted poor prognosis." (PMID 34422665, 2021).
gastric cancer (2 papers, 2017 to 2021). A primary or metastatic malignant neoplasm involving the stomach. "Additionally, our results indicated that E2 induced GPER and ARTN expression and enhanced tumor growth in the ovariectomized gastric cancer xenograft model." (PMID 34257587, 2021).
heart failure (2 papers, 2023 to 2024). Inability of the heart to pump blood at an adequate rate to meet tissue metabolic requirements. "Reverse Mendelian randomization suggested that the onset of heart failure might potentially influence the levels of four inflammatory factors, with ARTN and FGF5 decreasing after the onset of heart failure, and SLAM and MMP-10 increasing." (PMID 39726944, 2024). "In non-COVID-19 patients, elevated levels of artemin were associated with echocardiographic markers of heart failure in patients with rheumatoid arthritis." (PMID 37834869, 2023). "Moreover, reverse Mendelian randomization analysis identified inflammatory factors such as ARTN, FGF5, MMP-10, and SLAM, whose increased secretion may represent an adaptive response to heart failure." (PMID 39726944, 2024).
injury (2 papers, 2015 to 2017). Damage inflicted on the body as the direct or indirect result of an external force, with or without disruption of structural continuity. "Conversely, artemin is reported to have a pronociceptive role in peripheral inflammation or nerve injury." (PMID 25889103, 2015). "However, we found increased artemin synthesis in the peripheral tissue after inflammation or nerve injury, which may have an important role in the regulation of TRP channel expression, as is the case with NGF." (PMID 25889103, 2015).
laryngeal squamous cell carcinoma (2 papers, 2014 to 2020). A squamous cell carcinoma that arises from the larynx. "In laryngeal squamous cell carcinoma, the expression of GFRα1 and ARTN, another GFL member, was associated with more advanced pTNM stage." (PMID 32084217, 2020). "However, the clinical and prognostic significance of ARTN and its receptors has not yet been investigated in human laryngeal squamous cell carcinoma (LSCC)." (PMID 25120606, 2014).
liver cancer (2 papers, 2021 to 2024). An epithelial or non-epithelial malignant neoplasm that arises from the liver. "In liver cancer, artemin-positive, tumor-inducible, erythroblast-like cells (Ter-cells) could promote tumor progression, whereas an artemin deficiency abolishes the tumor-promoting effect." (PMID 34496868, 2021).
osteoporosis (2 papers, 2025). A condition of reduced bone mass, with decreased cortical thickness and a decrease in the number and size of the trabeculae of cancellous bone (but normal chemical composition), resulting in increased fracture incidence. "In contrast, higher concentrations of Artemin were inversely linked with osteoporosis risk, indicating a protective effect." (PMID 41329541, 2025). "Firstly, in terms of osteoporosis risk assessment, the 7 inflammatory factors we identified (Artemin, β-NGF, CXCL10, CXCL6, IL-10Rα, IL-10Rβ, LAP-TGFβ1) may become new biomarkers." (PMID 41261570, 2025). "Upon conducting a heterogeneity assessment, IL-19 was excluded from subsequent analysis due to significant heterogeneity, while the remaining two factors, IL-18 and Artemin, demonstrated remarkable links with osteoporosis." (PMID 41329541, 2025).
pancreatic adenocarcinoma (2 papers, 2020 to 2022). "Results from a study of pancreatic adenocarcinoma indicate that ARTN may have a significant role in tumor metastasis, particularly perineural invasion (PNI)." (PMID 36471885, 2022).
Pruritus (2 papers, 2021 to 2023). Pruritus is an itch or a sensation that makes a person want to scratch. "Another mediator of pruritus in AD may be artemin which belongs to the glial cell line-derived neurotrophic factor (GDNF)." (PMID 37834183, 2023). "In addition, artemin, a member of the GDNF family, is involved in hypersensitivity to warm sensations, mimicking warmth-provoked pruritus in AD." (PMID 34208021, 2021).
Anxiety (1 paper, 2025). Intense feelings of nervousness, tension, or panic often arise in response to interpersonal stresses. "The significant correlation observed here is that a decrease in artemin levels is associated with an increase in anxiety-like behavior." (PMID 40867635, 2025). "This study aimed to examine the levels of artemin, a neurotrophic factor in the neuroinflammation model, anhedonia, self-care, locomotor activity, and anxiety-like behaviors." (PMID 40867635, 2025). "For this purpose, ARTN levels in the prefrontal cortex (PFC) and striatum were investigated in correlation with different behavioral patterns, including self-care behavior and anxiety-like behavior, for the first time." (PMID 40867635, 2025).